FCGR1BP (Fc gamma receptor Ib, pseudogene)
Description:
May bind to the Fc region of immunoglobulins gamma with a low affinity compared to FCGR1A. May function in the humoral immune response.
Synonyms: CD64b; formerly FCGR1B
Gene: Transcribed unprocessed pseudogene on chromosome 1 (121,087,395 to 121,096,152, forward strand). Ensembl gene ENSG00000198019.
Subcellular location: Cell membrane
Pathways (Reactome):
Immune System: Cross-presentation of soluble exogenous antigens (endosomes); Interferon gamma signaling
Genetic constraint (gnomAD): Loss-of-function variants: 14 observed, 18.86 expected, observed/expected ratio (o/e) 0.74, 90% interval 0.49 to 1.16. The upper end of that interval is the gene's LOEUF score, 1.16, which puts it in group 5 of 6, group 1 being the genes least tolerant of losing a copy. Missense variants: 164 observed, 166.75 expected, observed/expected ratio (o/e) 0.98, 90% interval 0.87 to 1.12. Synonymous variants: 78 observed, 67.61 expected, observed/expected ratio (o/e) 1.15, 90% interval 0.96 to 1.39.